PAQR3 (progestin and adipoQ receptor family member 3)
Diseases named in the same sentence as PAQR3 in open-access papers (continued):
Sharing a sentence is not in itself a finding about the gene and the disease.
tumor (25 papers, 2015 to 2026). "This part of the analysis data also proved that PAQR3 is associated with the tumor microenvironment." (PMID 38321173, 2024). "Intriguingly, in vivo rescue assays showed that the knockdown of PAQR3 attenuated the inhibitory effects on tumor growth, LNM, and lung metastasis, caused by the overexpression of hsa_circ_0043280." (PMID 34588429, 2021). "A subcutaneous xenograft tumor model indicated that the overexpression of hsa_circ_0043280 led to suppression in tumor growth, while the knockdown of PAQR3 partially reversed the inhibition of tumor growth caused by the overexpression of has_circ_0043280." (PMID 34588429, 2021). "The expression of progestin and adipoQ receptor 3 (PAQR3) is generally downregulated in multiple tumors, which is associated with tumor progression and poor prognosis." (PMID 33123538, 2020). "Secondly, although we found that PAQR3 is associated with the regulation of tumor microenvironment, the specific regulatory mechanism remains unclear." (PMID 38321173, 2024). "Therefore, our experiments successfully identified the mechanism underlying the tumor suppression caused by hsa_circ_0043280 and expanded our knowledge relating to the function of PAQR3 in the progression of CCa." (PMID 34588429, 2021). "It is currently unknown whether the tumor suppressive activity of PAQR3 is associated with its regulatory function on ER-to-Golgi trafficking." (PMID 30466064, 2018). "Therefore, whether PAQR3 is associated with the tumor immune microenvironment remains a question to be explored in future studies." (PMID 40723340, 2025). "Mechanistic investigations involving functional assays demonstrated that PAQR3 exerts anti-tumor effects by suppressing the PI3K-AKT signaling axis." (PMID 40723340, 2025). "Of the 9 articles analyzed, 5 studies reported a significant correlation between decreased expression of PAQR3 and tumor size in cancer patients (HR = 0.73, 95%CI: 0.36-1.5)." (PMID 40391162, 2025). "In conclusion, this study highlights the tumor-suppressive role of PAQR3 in CRC and reveals its regulatory impact on key oncogenic pathways." (PMID 40723340, 2025). "To further elucidate the tumor-suppressive mechanism of PAQR3, we conducted in vivo experiments, complemented by RNA sequencing and detailed data analysis." (PMID 40723340, 2025). "Using multi-database transcriptome data to analyze the difference in PAQR3 expression between tumor tissues and normal tissues, we found that PAQR3 was significantly overexpressed in CHOL, ESCA, HNSC, LIHC, LUAD and LUSC." (PMID 38321173, 2024). "The results also showed that patients with high PAQR3 expression in BRCA, KIRC, KIRP, and LIHC tumors had worse OS, indicating that PAQR3 was a risk factor affecting prognosis in these tumor types." (PMID 38321173, 2024). "UALCAN database was used to analyze the methylation level of PAQR3 gene promoter, and the analysis showed that in 10 types of tumors, PAQR3 promoter methylation level in tumor tissues showed significant changes compared with normal tissues." (PMID 38321173, 2024). "Circ_0043280 regulates CC through the miR-203a-3p/PAQR3 axis, competitively binding miR-203a-3p and restoring PAQR3 expression, thereby preventing tumor growth and metastasis." (PMID 38434620, 2024). "This indicates that PAQR3 affects the occurrence and development of tumors through different pathways in different types of tumor tissues." (PMID 38321173, 2024).
tumor (continued). "The TISIDB immunological website found that PAQR3 expression level was diverse in different immune subtypes of the same tumor." (PMID 38321173, 2024). "Based on these studies, we found that PAQR3 plays an important role in cancer and has potential in tumor diagnosis and prognosis." (PMID 38321173, 2024). "This research makes a systematic and comprehensive study of the correlation between PAQR3 expression profile, prognostic significance, and tumor microenvironment by bioinformatics methods." (PMID 38321173, 2024). "Studies of this molecule PAQR3 in specific tumor types have shown that PAQR3 is involved in the generation of tumor drug resistance and the regulation of cell death." (PMID 38321173, 2024). "We explored the effect of PAQR3 protein expression levels in tumor tissues on the overall survival (OS) of GCA patients." (PMID 35870178, 2022). "RKTG/PAQR3 expression inversely correlates with cancer malignancy and poor prognosis, thus suggesting that RKTG/PAQR3 acts as a tumor suppressor." (PMID 35805075, 2022). "PAQR family contains eleven members, and previous studies have focused more on PAQR3, a novel tumor suppressor gene that is downregulated in different types of human cancers." (PMID 36481756, 2022). "Accumulating evidence indicates that PAQR3 is downregulated in various tumors and inhibits tumor growth and metastasis by altering pathological signaling pathways." (PMID 34588429, 2021). "PAQR3, a membrane protein of the Golgi body, has been reported to act as a tumor suppressor and negatively regulated to numerous human cancers." (PMID 34588429, 2021). "PAQR3 (also named RKTG) has been proved to take part in many human cancers by acting as a tumor suppressor." (PMID 33955706, 2021). "The expression of PAQR3 is decreased and closely associated with serum alpha-fetoprotein (AFP), clinical stage, tumor size, and survival time in hepatocellular carcinoma." (PMID 33123538, 2020). "In summary, the expressions of PAQR3 mRNA and protein were downregulated and was significantly related to tumor size, histological subtype, and lymph node metastasis in NSCLC patients." (PMID 33123538, 2020). "PAQR3 was demonstrated to suppress the tumor progression of NSCLC cells by modulating EGFR-regulated autophagy." (PMID 32190662, 2020). "Progesterone and adiponectin receptor family member 3 (PAQR3) is a recently discovered tumor suppressor gene, which affects the development of a tumor by inhibiting cell proliferation, cell malignant transformation, angiogenesis, and tumor metastasis." (PMID 28442015, 2017). "The positive expression rate of PAQR3 protein was unrelated to age, tumor size, and gender, but it exhibited a significant relationship with the pathological type and differentiation, TNM staging, and lymph node metastasis (P < 0.05)." (PMID 28442015, 2017). "In a tumor xenograft model, overexpression of PAQR3 suppresses tumor growth of PC3 cells in vivo, while PAQR3 knockdown promotes the tumor growth." (PMID 28903314, 2017). "PAQR3 also has a suppressive activity in chemical carcinogen-induced mitogenesis and tumor formation in mouse skin." (PMID 25900239, 2015). "PAQR3 functions as a tumor suppressor mainly due to its inhibitory activity on Raf/MAPK and PI3K/Akt signaling pathways." (PMID 25900239, 2015). "Moreover, our experimental results demonstrated that PAQR3 overexpression significantly reduced the colony-forming ability of these cancer cells, highlighting its important role in inhibiting tumor growth." (PMID 40723340, 2025). "Given that the KEGG classification diagram indicated significant enrichment of the PI3K-AKT signaling pathway following PAQR3 knockdown, we further explored whether PAQR3 knockdown regulates this pathway, thereby influencing tumor growth." (PMID 40723340, 2025).
tumor (continued). "Additionally, we observed that the expressions of the cell adhesion-related genes FN1 and LAMB1 were upregulated after PAQR3 knockdown, aligning with the biological function of PAQR3 as a tumor suppressor gene." (PMID 40723340, 2025). "PAQR3 plays a crucial tumor-suppressive role across various cancer types." (PMID 40723340, 2025). "The methylation level of PAQR3 promoter in tumor tissues was significantly higher than that in normal tissues in COAD and ESCA, while the opposite was true in BLCA, PRAD and UCEC, and the methylation level of PAQR3 promoter in tumor tissues was significantly lower than that in normal tissues." (PMID 38321173, 2024). "We found that the expression level of PAQR3 was significantly different in different immune subtypes, suggesting that PAQR3 may be involved in the immune regulation of tumor microenvironment and promote the differentiation of TME to different immune subtypes." (PMID 38321173, 2024). "Finally, we investigated the role of PAQR3 in tumor resistance and found that the expression of PAQR3 affects the efficacy of multiple chemotherapy drugs." (PMID 38321173, 2024). "Furthermore, the differential expression of PAQR3 in tumor tissues and normal tissues was analyzed by GEPIA2." (PMID 38321173, 2024). "In summary, PAQR3 can affect the tumor microenvironment and has potential for chemotherapy." (PMID 38321173, 2024). "Downregulation of PAQR3 expression was closely related with tumor progression." (PMID 35870178, 2022). "Therefore, PAQR3 is considered as a novel and important gene with multiple tumor suppressor functions in GC." (PMID 35870178, 2022). "PAQR3 as a novel tumor suppressor gene can inhibit multiple tumorigenesis and development by regulating multiple signaling pathways, but whether PAQR3 can regulate TGF‐β signaling to influence the progression of GCA is unknown." (PMID 35870178, 2022). "However, the correlation between the PAQR3 expression levels in the tumor tissues and the survival of the GCA patients depends on the tumor stage." (PMID 35870178, 2022). "Thus, our results suggest that the downregulation of PAQR3 in GCA tissues promotes tumor progression and metastasis, which is closely related to activation of TGF‐β/Smad signaling, subsequently mediating increased EMT phenotype characteristics." (PMID 35870178, 2022). "PAQR3 is a recently identified gene with a variety of potential tumor suppressor functions." (PMID 35870178, 2022). "Moreover, the knockdown of PAQR3 partially rescued tumor weight and size; these parameters were both suppressed by the overexpression of hsa_circ_0043280." (PMID 34588429, 2021). "Therefore, we concluded that PAQR3 acted as a tumor suppressor in the progression of NSCLC and was expected to be a potential marker for prognosis and diagnosis in NSCLC." (PMID 33123538, 2020). "Progestin and adipoQ receptor 3 (PAQR3) is a newly discovered tumor suppressor." (PMID 33123538, 2020). "However, in the 60 clinical samples, the level of PAQR3 mRNA was only significantly correlated with tumor size (P < 0.05)." (PMID 33123538, 2020). "CUL4A may also play a crucial role in the regulation of PAQR3 (progestin and adipoQ receptor family member III), a newly discovered tumor suppressor that exerts its biological function through negative regulation of the oncogenic Raf/MEK/ERK signaling." (PMID 29594129, 2018). "The tumor size, tumor weight and tumor volume were all increased by PAQR3 knockdown in the mice." (PMID 28903314, 2017). "We also investigated the effect of PAQR3 knockdown on tumor growth in vivo." (PMID 28903314, 2017). "However, it remains crucial to investigate whether PAQR3 and its synthetic peptide (P6-55) exhibit similar tumor-suppressive properties in CRC." (PMID 40723340, 2025).
tumor (continued). "If we want to explore whether the role of PAQR3 in various cancers is universal and which tumors can be used as prognostic or therapeutic markers, we still need to analyze the correlation between PAQR3 expression at the pan-cancer level, prognostic indicators, and tumor microenvironment." (PMID 38321173, 2024). "Besides the level of PAQR3 expression in tumor tissues affects the prognosis of GCA patients, these clinicopathological features, including distant metastasis, T stage, venous infiltration, and TNM stage, all have significant effects on the prognosis of GCA patients." (PMID 35870178, 2022). "Moreover, we found that hsa_circ_0043280 could suppress tumor growth and metastasis in CCa by modulating the expression of PAQR3." (PMID 34588429, 2021). "Moreover, hsa_circ_0043280 could competitively bind miR-203a-3p to restore the expression of PAQR3, thus inhibiting tumor growth and metastasis in CCa." (PMID 34588429, 2021). "However, to date, numerous studies have reported that PAQR3 is a newly discovered tumor suppressor." (PMID 33123538, 2020). "Previous studies confirmed that PAQR3, a new tumor suppression gene, may regulate inflammation." (PMID 29930535, 2018). "RNA sequencing indicated that PAQR3 suppresses tumor growth via the PI3K-AKT signaling pathway, providing a theoretical basis for therapeutic strategies targeting PAQR3/P6-55." (PMID 40723340, 2025). "RNA sequencing revealed that PAQR3 suppresses tumor growth via the PI3K-AKT signaling pathway, providing a strong theoretical foundation for therapeutic strategies targeting PAQR3/P6-55." (PMID 40723340, 2025). "In this study, we found that the expression level of PAQR3 was significantly related to TMB, MSI and NEO in more than 10 kinds of tumors, and was closely related to tumor purity in 25 kinds of tumors." (PMID 38321173, 2024). "The Stromal Score and Immune Score of tumor were analyzed by ESTIMATTE, and the correlation between them and the expression of PAQR3 was studied." (PMID 38321173, 2024). "We also analyzed the effect of PAQR3 on epithelial-mesenchymal transition (EMT), a critical step for tumor migration and metastasis." (PMID 28903314, 2017). "PAQR3 (Progestin and adipoQ receptor 3)—also known as RKTG (Raf Kinase Trapping to Golgi)—is a key member of the PAQR family and widely recognized for its role as a tumor suppressor." (PMID 40723340, 2025). "However, the expression levels of PAQR3 RNA in HNSC, LIHC, LUAD and LUSC tumor tissues are very different, which may indicate that the current classification criteria cannot accurately separate the subgroups with low expression of PAQR3 from those with high expression of PAQR3 in tumor groups." (PMID 38321173, 2024). "Especially, PAQR3, the closest homologue of PAQR4, has been recently discovered as a novel tumor suppressor deregulated in various types of human cancers including colon cancer, gastric cancer, bladder cancer, liver cancer, osteosarcoma, breast cancer, and laryngeal squamous cell carcinoma 25-30." (PMID 32206121, 2020). "In summary, PAQR3 played a role in the occurrence and development of all reported cancers as a tumor suppressor gene, and no opposite effect has been found." (PMID 33123538, 2020). "However, the clinical importance of PAQR3 in the prognosis of tumor patients has not yet been completely analyzed via meta-analysis." (PMID 40391162, 2025). "Interestingly, PAQR3 a Golgi scaffolding protein (also named RKTG for Raf kinase trapping to the Golgi) is actively involved in the degradation of Twist1, a critical transcription factor required for the initiation of EMT and metastasis of tumor cells." (PMID 34957124, 2021). "PAQR3 expression did not significantly affect OS and DFS in the remaining tumor types." (PMID 38321173, 2024).
cancer (14 papers, 2015 to 2026). A tumor composed of atypical neoplastic, often pleomorphic cells that invade other tissues. "Subsequently, mounting evidence has revealed that PAQR3 not only regulates the MAPK pathway but is also closely associated with multiple core cancer pathways, including PI3K-AKT, NF-κB, and TGF-β/Smad." (PMID 40723340, 2025). "The PAQR3 genomic alteration in pan-cancer was analyzed by cBioPortal database, and it was found that 1% of patients had PAQR3 genomic mutation, Amplification was the most dominant type of mutation in PAQR3, followed by Deep Deletion and Missense Mutation." (PMID 38321173, 2024). "Progestin and adipoQ receptor family member 3 (PAQR3) expression is significantly associated with advanced TNM stage of cancer." (PMID 31244652, 2019). "In conclusion, reduced PAQR3 expression in pan-cancer patients is associated with worse clinical outcomes and may promote cancer progression." (PMID 40391162, 2025). "The results demonstrated that high PAQR3 expression was significantly associated with improved overall survival (HR = 0.32; 95% CI = 0.19–0.56) and disease-free survival (HR = 0.35; 95% CI = 0.20–0.61) in pan-cancer patients." (PMID 40391162, 2025). "This review aims to summarize the expression patterns, regulatory mechanisms, key downstream pathways, and clinical significance of PAQR3 in cancer." (PMID 41609065, 2026). "In the present study, meta-analysis results implied that high expression of PAQR3 can delay cancer progression and improve cancer prognosis." (PMID 40391162, 2025). "Lastly, 1 study reported a significant correlation between the expression level of PAQR3 and invasion depth in cancer patients (HR = 0.18, 95%CI: 0.11-0.29)." (PMID 40391162, 2025). "This study demonstrated that the abnormal expression of PAQR3 triggers significant cancer progression, as evidenced by the results of the RNA-seq analysis and functional assays." (PMID 40723340, 2025). "All these six articles explored the relationship between PAQR3 levels and the OS and four studies investigated the association between PAQR3 levels and DFS of cancer patients." (PMID 40391162, 2025). "Overall, this meta-analysis confirms downregulation of PAQR3 expression is related to poor prognosis in patients with pan-cancer." (PMID 40391162, 2025). "In this study, we analyzed 1032 patients with pan-cancer included in 9 different studies using meta-analysis and found that PAQR3 overexpression was significantly related to improved OS and DFS of these patients." (PMID 40391162, 2025). "The data showed that the expression level of PAQR3, as a cancer promoting factor, was correlated with the OS of THCA." (PMID 38321173, 2024). "This study will provide a new perspective for the research of PAQR3 in cancer and a new idea for the early diagnosis and treatment of cancer." (PMID 38321173, 2024). "We found widespread and significant changes in PAQR3 expression level in the TCGA and GTEx databases in pan-cancer." (PMID 38321173, 2024). "Then, we analyzed the differential expression of PAQR3 in pan-cancer in the TCGA database, and the data suggested that the expression level of PAQR3 in CHOL, ESCA, HNSC, LIHC, LUAD and LUSC tumors was significantly higher than that in normal tissues." (PMID 38321173, 2024). "We first analyzed PAQR3 expression levels in pan-cancer cell lines using the CCLE database, and the results showed that PAQR3 expression level varied." (PMID 38321173, 2024). "PAQR3 has been shown to induce apoptosis and inhibit proliferation and invasiveness of cancer cells when its expression is restored." (PMID 37711170, 2023).